Y_RNA (Y RNA )
Gene: Miscellaneous RNA gene on chromosome 3 (195,419,436 to 195,419,546, reverse strand). Ensembl gene ENSG00000207368.
Homologues: Orthologues: chimpanzee Y_RNA (94% identical), macaque Y_RNA (93% identical). Paralogues in human: RNY1 (88% identical), Y_RNA (87% identical), Y_RNA (86% identical), RNY1P8 (86% identical), Y_RNA (85% identical), RNY1P11 (84% identical), Y_RNA (84% identical), Y_RNA (83% identical), Y_RNA (82% identical), RNY1P10 (81% identical), RNY1P2 (81% identical), RNY1P5 (81% identical), and 96 more.